TFAM (transcription factor A, mitochondrial)
Diseases named in the same sentence as TFAM in open-access papers (continued):
Sharing a sentence is not in itself a finding about the gene and the disease.
osteosarcoma (7 papers, 2020 to 2024). A usually aggressive malignant bone-forming mesenchymal neoplasm, predominantly affecting adolescents and young adults. "Reduced TFAM gene expression in drug-resistant cells is often associated with mitochondrial biogenesis, and combining doxorubicin (a chemotherapy drug) with quercetin (a known inducer of mitochondrial biogenesis) Drug-resistant osteosarcoma cells can be resensitized to doxorubicin." (PMID 39445018, 2024). "We detected co-immunofluorescence of C17orf80, mtDNA, and a mitochondrial marker cyclophilin D (CypD) or the nucleoid marker TFAM in human osteosarcoma cells (U2OS)." (PMID 37401363, 2023). "To this end, we evaluated the viability of the human osteosarcoma 143B cells after inactivating TFAM, POLRMT, TFB2M, POLG, POLG2, or SSBP1 with CRISPR-Cas9." (PMID 35883613, 2022). "For these studies, we employed human 143B osteosarcoma cells with mutant TFAM." (PMID 37031254, 2023). "Interestingly, our data demonstrated that DXR-resistant osteosarcoma cells decreased mRNA levels of TFAM gene compared to their sensitive counterpart, thus suggesting that the downregulation of mitochondrial biogenesis could be the process involved in the DXR resistance onset." (PMID 36900165, 2023).
acute kidney injury (6 papers, 2022 to 2026). Sudden and sustained deterioration of the kidney function characterized by decreased glomerular filtration rate, increased serum creatinine or oliguria. "In addition, it has been shown that alterations in TFAM levels or mtDNA copy number are associated with acute renal failure, tumor progression, skeletal muscle atrophy, ischemic and nonischemic cardiac dysfunction, neurodegeneration and many other diseases." (PMID 39701936, 2024). "In line with our results, a direct regulation of TFAM transcription by C/EBPβ in the inflammatory context induced in acute kidney injury has also been described." (PMID 36674978, 2023). "It has been shown that the interaction between C/EBPβ and TFAM activates NLRP3/caspase-1 and promotes the development of acute kidney injury." (PMID 37624173, 2023).
colitis (6 papers, 2022 to 2024). Inflammation of the colon. "TFAM knockdown increases the susceptibility to azoxymethane/DSS-induced CAC in mice, and TFAM overexpression prevents intestinal inflammation and colitis-related tumorigenesis in mice." (PMID 36499214, 2022). "Because BBR contains vitamin A, which increases mitochondrial transcription factors and NFRS—1 TFAM, efficiently protects colon mitochondria, prevents inflammation and colitis necrosis, and reverses the process of mitochondrial damage." (PMID 39268532, 2024). "NR treatment not only reduced DAI scores, but also increased the expression of PGC1α and TFAM, as well as the activity of Complex I and II in mice undergoing experimental colitis, indicating that NR treatment increased the NAD+ levels within the colonocytes." (PMID 37744380, 2023). "The loss of Tfam in Treg affects Treg homing and stability, thus leading to tissue inflammation in colitis, but enhances tumor rejection, which reveals the key role of TFAM-mediated mitochondrial respiration in regulating inflammation and anti-tumor immunity in Tregs." (PMID 38415258, 2024). "Here we demonstrated that TFAM is highly expressed in ILC3s and acts as a key downstream effector of NPM1 in DSS-induced colitis." (PMID 39103576, 2024). "In order to assess if NR treatment restores the SIRT1-PGC1α axis during experimental colitis, we assessed the expression levels of SIRT1, PGC1α, and TFAM in DSS+NR and DSS+Vehicle mice." (PMID 37744380, 2023). "Although there is no direct evidence that TFAM regulates IL-22, the lack of mitochondrial-derived energy by insufficient TFAM could limit the activation of ILC3s and effector cytokine secretion in colitis." (PMID 39103576, 2024). "Accordingly, NPM1 is crucial for the heightened demand of TFAM to subsequently increase mitochondrial function in ILC3s, not other cell types, during DSS-induced colitis." (PMID 39103576, 2024).
esophageal squamous cell carcinoma (6 papers, 2017 to 2025). Esophageal squamous cell carcinoma (ESCC) is a type of esophageal carcinoma (EC) that can affect any part of the esophagus, but is usually located in the upper or middle third. "Conversely, knockdown of mitochondrial transcription factor A (TFAM) leads to a decrease in mtDNA copy number, upregulation of E-cadherin expression, and suppression of cell migration rate in esophageal squamous cell carcinoma." (PMID 31921862, 2019). "A notable decrease in TFAM levels have been reported in tissue collected from patients with esophageal squamous cell carcinoma (ESCC) and the ESCC cell line, KYSE-140." (PMID 39050748, 2024). "Surprisingly, our data show that TFAM silencing in U87MG GBM cells increased cell viability, consistent with reports in esophageal squamous cell carcinoma and head and neck cancers." (PMID 41226485, 2025).
gastric cancer (6 papers, 2017 to 2025). A primary or metastatic malignant neoplasm involving the stomach. "Furthermore, to understand the clinical significance of TFAM expression in cancer, we tested whether TFAM polymorphisms were associated with susceptibility to gastric cancer." (PMID 29259235, 2017). "The gastric cancer cell line AGS was used with knockdown (KD) mitochondrial transcription factor A (TFAM) to achieve mitochondrial dysfunction through a decrease of mtDNA copy number." (PMID 35163779, 2022). "For example, antisense oligonucleotides were used to decrease the expression of TFAM in injured rat carotid arteries and knockdown of TFAM in gastric cancer cells resulted in decreased cell proliferation." (PMID 32824374, 2020). "In this study, we analyzed the effects of TFAM depletion on gastric cancer MKN45 cells to gain insight into the functional role of TFAM in human cancer." (PMID 29259235, 2017). "Likewise, in this study, TFAM knockdown using either siTFAM#1 or siTFAM#2 decreased the proliferation of MKN45 gastric cancer cells." (PMID 29259235, 2017). "Furthermore, according to the ONCOMINE microarray data, TFAM is upregulated in several cancer tissues, including gastric cancer tissues." (PMID 29259235, 2017). "In this study, we investigated the effects of TFAM depletion on the morphology and transcriptome of MKN45 gastric cancer cells." (PMID 29259235, 2017).
glioblastoma (6 papers, 2018 to 2025). The most malignant astrocytic tumor (WHO grade IV). "Evidence indicates that TFAM has been shown to regulate mtDNA copy number, and an unbalance in the number of mtDNA copies is associated with several neurodegenerative diseases and cancer, including glioblastoma." (PMID 29747444, 2018). "Overexpressing FoxM1 increased TFAM protein levels, which was reversed by FoxM1 knockdown in glioblastoma multiforme (GBM) cells." (PMID 41323781, 2025). "In conclusion, elucidating the effect of melatonin on TFAM expression should help to understand the signaling pathways involved in glioblastoma progression, and melatonin could be potentially applied in the treatment of this type of brain tumor." (PMID 29747444, 2018). "Thus, we hypothesized that melatonin decreases the expression of TFAM (RNA and protein) in the human glioblastoma cell line U87MG, which disrupts mtDNA expression and results in cell death due to increased ROS production and mitochondrial damage." (PMID 29747444, 2018). "In summary, our results suggest that increased generation of melatonin-induced intracellular ROS in U87MG glioblastoma cells may be an effect of melatonin on the expression of TFAM and other mitochondrial transcription factors (TFB1M and TFB2M), leading to mitochondrial disruption." (PMID 29747444, 2018). "Mitochondrial transcription factor A (TFAM) is essential for mitochondrial DNA (mtDNA) maintenance and function, but its role in glioblastoma (GBM) remains largely unexplored." (PMID 41226485, 2025). "VEGFR2 blockade inhibits glioblastoma progression via AKT-PGC1α-TFAM-mitochondria biogenesis signaling cascade, suggesting that VEGFR2 intervention might bring additive therapeutic values to anti-glioblastoma therapy." (PMID 38702818, 2024). "In the present study, we showed that TFAM and other mitochondrial transcription factors (TFB1M and TFB2M) may be targets of melatonin in glioblastoma cells." (PMID 29747444, 2018). "Furthermore, a single-nucleotide deletion was identified in exon 4 of TFAM in a patient with glioblastoma IV, while no large-scale mtDNA deletions were found in brain tumor patients." (PMID 39128073, 2024).
Huntington disease (6 papers, 2011 to 2023). Huntington disease (HD) is a rare neurodegenerative disorder of the central nervous system characterized by unwanted choreatic movements, behavioral and psychiatric disturbances and dementia. "A decrease of mtDNA and TFAM levels in patients and animal models of neurodegenerative disorders such as PD, AD, Huntington’s disease (HD), and ALS has been described, revealing the involvement of TFAM in neurodegeneration." (PMID 36674978, 2023).
renal fibrosis (6 papers, 2021 to 2025). A final common manifestation of a wide variety of chronic kidney diseases characterized by glomerulosclerosis and tubulointerstitial fibrosis. "Tubule-specific deletion of TFAM has been related to an increase in renal fibrosis, thus supporting the profibrotic phenotype found in these mice." (PMID 37487638, 2023). "Loss in tubular cells of PGC-1α and mitochondrial transcription factor A (TFAM), which are transcriptional regulators of MB, increased susceptibility to AKI and renal fibrosis." (PMID 37371668, 2023). "Mechanistically, TFAM deficiency causes mtDNA mispackaging and leaking into the cytosol resulting in the activation of cGAS-STING pathway and the upregulation of downstream NF-κB which underlies the renal fibrosis and inflammation in CKD progression." (PMID 34306320, 2021).
liver failure (5 papers, 2021 to 2024). A liver disease characterized by the liver losing or has lost all of its function. "For example, a deficiency in human TFAM has been identified as a catalyst for mitochondrial dysfunction and a reduction in nucleoid formation, culminating in fatal liver failure." (PMID 38476236, 2024). "Postnatal developmental disturbances were also observed in two rare cases of a homozygous missense variant in TFAM, where an 89% reduction in mtDNA content in the patient’s liver and 79% in muscle led to liver failure and neonatal death." (PMID 35054416, 2021). "Differential diagnosis should also be considered with other mitochondrial disorders causing liver failure (MPV17, POLG1, POLG2, TFAM, TWNK, TRMU)." (PMID 38756539, 2024). "Mitochondrial transcription factor A (TFAM) deficiency may cause mtDNA depletion syndrome, which manifests as neonatal liver failure or primary ovarian insufficiency, hearing loss, seizures, and intellectual disability." (PMID 39716297, 2024).
pancreatic cancer (5 papers, 2021 to 2025). "Major mitochondrial genes including MT-ND3, MT-CO1, IDH2, and TFAM are being reported in various pancreatic cancers, including PDAC (based on cBioportal data), but their actual roles in PDAC progression need further validation." (PMID 36831413, 2023).
renal cell carcinoma (5 papers, 2018 to 2025). "In 769-P renal cell carcinoma cells, overexpression of FTO leads to the upregulation of PGC1A, TFAM, and NRF1 genes, which are involved in mitochondrial biogenesis." (PMID 40361322, 2025).
sarcopenia (5 papers, 2019 to 2025). Progressive decline in muscle mass due to aging which results in decreased functional capacity of muscles. "NRF-1, TFAM and mtDNA represent the dysregulation of mitochondrial quality control processes and contribute to sarcopenia." (PMID 35631191, 2022). "The expression levels of PGC-1α, NRF1, and TFAM are decreased in the skeletal muscle of senescence-accelerated mouse (SAM) prone 8 (SAMP8) during the onset and development of sarcopenia." (PMID 37152937, 2023). "NRF2 knockout exacerbated frailty and sarcopenia of mice during aging, accompanied by the reduced expression levels of PGC-1α, NRF1, and TFAM, as well as a reduction of mitochondrial content in the skeletal muscle." (PMID 37152937, 2023). "Concurrently, mitochondrial biogenesis, the process of forming new mitochondria, regulated by master factors such as peroxisome proliferator-activated receptor-gamma coactivator-1alpha (PGC-1alpha) and mitochondrial transcription factor A (TFAM), also declines with age in sarcopenia." (PMID 41568334, 2025).
viral infection (5 papers, 2019 to 2026). "So the depletion of TFAM in response to virus infection is potentially associated with priming the antiviral innate immune response." (PMID 31011285, 2019). "The aberrant expression of certain components in the RC complexes and antioxidant enzymes as well as the NRF1/2/TFAM signaling correlated well with a previous report that virus infection stimulates excessive ROS production and mitochondrial dysfunction." (PMID 31011285, 2019). "The virus infection consistently increased the expression of TFAM from 2 h after infection and peaked at 16 h after infection, with a level increased to approximately 164.4% (p < 0.05) relative to the control." (PMID 31011285, 2019). "However, the increased expression of TFAM corroborated well with our findings that virus infection enhanced the expression of SDHB and MTCO1, components in mitochondrial RC complexes." (PMID 31011285, 2019). "While the expression levels of TFAM, an executor of the canonical PGC-1α pathway, were consistently increased from 2 to 16 h after infection, suggesting that virus infection promotes TFAM expression with an unknown mechanism that is independent on either NRF1 or NRF2." (PMID 31011285, 2019). "Downregulation of mitochondrial transcription factor A (TFAM), triggered by nutrient stress and viral infection, impairs mtDNA stability and promotes its release." (PMID 41601699, 2026). "Furthermore, DPI treatment demonstrated minor effects on the expression of TFAM in the context of virus infection, though DPI treatment led to an increased level of TFAM protein in mock-infected cells." (PMID 31011285, 2019). "Induced imbalance in these processes by either viral infection (i.e. HIV or HCV) and/or injection drug use related stressors could result in ROS-mediated nucleoid clustering by targeting mtDNA stabilization proteins such as TFAM, which would then potentially affect mtDNA replication." (PMID 37891237, 2023). "Interestingly, the virus infection at the late stage (at 16 h after infection) stimulated TFAM expression but decreased the levels of both NRF1 and NRF2, indicating that virus infection activated TFAM signaling independent of either NRF1 or NRF2." (PMID 31011285, 2019).
astrocytomas (4 papers, 2016 to 2025). "We previously reported that TFAM expression declines with increasing tumor grade, with low-grade astrocytomas (AG2 and AG3) exhibiting higher levels than GBM (AG4)." (PMID 41226485, 2025). "Consistent with this, our group previously demonstrated a progressive decrease in TFAM mRNA levels with increasing astrocytoma malignancy, reaching the lowest levels in GBM, particularly in the MS and GPM subtypes—those associated with the worst prognosis." (PMID 41226485, 2025). "Analysis of patient astrocytomas and TCGA datasets has revealed progressive TFAM downregulation with increasing malignancy, with the lowest expression in glycolytic/plurimetabolic (GPM) subtypes." (PMID 41226485, 2025). "This trend was confirmed in The Cancer Genome Atlas (TCGA) dataset, comprising 363 astrocytomas (65 AG2, 131 AG3, and 167 GBM), where TFAM expression was again significantly higher in both AG2 (p < 0.0001) and AG3 (p = 0.0006) relative to GBM." (PMID 41226485, 2025). "The differential expression of TFAM in the REMBRANDT cohort was analyzed and found to have significantly higher TFAM gene transcript levels in GBM, astrocytoma, and oligodendroglioma than normal controls (p < 0.0001)." (PMID 37332990, 2023). "In malignant astrocytoma cells, decreased mtDNA copy numbers correlate with increased levels of mitochondrial POLG and mitochondrial transcription factors (TFAM, and TFB1M, and TFB2M)." (PMID 27486856, 2016). "A previous study reported high relative gene expression for TFAM and POLG in human astrocytomas." (PMID 29137431, 2017).
cognitive deficits (4 papers, 2012 to 2023). "Besides preventing cognitive impairment and neurodegeneration through its antioxidant and anti-inflammatory properties, resveratrol has been shown to be able to enhance mitochondria biogenesis by acting on its main effectors, including PGC-1α, SIRT1, AMPK, ERRs, TERT, TFAM, NRF-1 and NRF-2." (PMID 36237161, 2023).
dilated cardiomyopathy (4 papers, 2017 to 2023). Cardiomyopathy which is characterized by dilation and contractile dysfunction of the left and right ventricles. "Neonatal TFAM inactivation by AAV9-cTnT-Cre caused progressive, lethal dilated cardiomyopathy, while postnatal TFAM inactivation and disruption of mitochondrial function did not impair CM maturation." (PMID 34572112, 2021). "Other cardiomyocyte-specific TFAM knockout mouse models further characterized the effect of TFAM inactivation on mitochondrial cardiomyopathy with the development of dilated cardiomyopathy (DCM)." (PMID 34392401, 2021).
head and neck cancer (4 papers, 2023 to 2025). A primary or metastatic malignant neoplasm affecting the head and neck. "While down-regulation of TFAM suppressed the proliferation of HepG2 and U-2 OS cells, loss of TFAM facilitates the malignancy of head and neck cancer." (PMID 38429817, 2024). "Our findings suggest that variants in the TFAM gene may play an important role in head and neck cancer patient survival and could be considered and further evaluated as prognostic biomarkers." (PMID 36833361, 2023). "Despite these limitations, our results suggest that mitochondrial transcription factor A, encoded by the nuclear TFAM gene, may play an important role in head and neck cancer patient survival and could potentially serve as a prognostic survival biomarker." (PMID 36833361, 2023). "In this study, we aimed to analyze mitochondria-related mitochondrial transcription factor A (TFAM) and DNA polymerase γ (POLG) single-nucleotide polymorphisms (SNPs) in the head and neck cancer patient group and evaluate associations between SNPs, disease characteristics, and patient outcomes." (PMID 36833361, 2023). "There are no previous studies of the selected TFAM and POLG polymorphisms in head and neck cancer patients." (PMID 36833361, 2023).
Hepatic steatosis (4 papers, 2020 to 2022). Steatosis is a term used to denote lipid accumulation within hepatocytes. "Furthermore, compared with the control group, hepatic steatosis (fatty liver group) led to decreased mRNA abundance of RXRα, ACO, CPT1, CPT2, LCAD, Nrf1 and TFAM (p < 0.05 or p < 0.01)." (PMID 32230804, 2020). "However, it was reported that the protein levels of PGC-1α decreased in mice with fatty liver followed by reduction of NRF1 and TFAM, the mRNA abundance of PGC-1α increased." (PMID 32230804, 2020).
Hypertension (4 papers, 2020 to 2025). The presence of chronic increased pressure in the systemic arterial system. "Oral administration of a HMG-CoA reductase inhibitor, simvastatin, or an AMPK activator, metformin, to young HFD offspring reversed maternal HFD-programmed increase in AT1R and decreases in SIRT1, PGC-1α and TFAM; alleviated ROS production in RVLM, and attenuated sympathoexcitation and hypertension." (PMID 32446297, 2020).
mtDNA depletion syndrome (4 papers, 2017 to 2024). "Many of the significant genes have known mitochondrial functions, notably the mtDNA transcription factor TFAM (p = 1.09 × 10–29) and mitochondrial exonuclease MGME1 (p = 5.87 × 10–23), genes known as causal for mtDNA depletion syndromes." (PMID 34859289, 2022).